CCNE1 (cyclin E1)
Diseases named in the same sentence as CCNE1 in open-access papers (continued):
Sharing a sentence is not in itself a finding about the gene and the disease.
non-small cell lung carcinoma (17 papers, 2008 to 2024). A group of at least three distinct histological types of lung cancer, including non-small cell squamous cell carcinoma, adenocarcinoma, and large cell carcinoma. "Overexpression of miR-21 in non-small cell lung cancer up-regulated the expression of cyclin D1 and cyclin E1, respectively." (PMID 35154284, 2022). "Circ_0062389, as a member of circRNAs, regulates CCNE1 expression by adsorbing miR-103a-3p to promote the progression of non-small cell lung cancer (NSCLC)." (PMID 33926347, 2021). "Recently, our group demonstrated that ZYG11A serves as an oncogene in non-small cell lung cancer via regulating CCNE1 expression." (PMID 27107416, 2016). "CCNE1 has been reported as an independent, unfavorable prognostic indicator in breast and Non-Small Cell Lung cancer." (PMID 25408144, 2014). "MiR-21 was overexpressed in human non-small cell lung cancer (NSCLC) cells, and overexpressed miRNA-21 induced cyclin D1 and cyclin E1 expression and promoted proliferation of cancer cells." (PMID 34299149, 2021). "CDR1as acts as miR-7 sponges to upregulate targets of miR-7 including EGFR, CCNE1, and PIK3CD in non-small-cell lung cancer." (PMID 34221006, 2021). "Downregulation of CCNE1 and CCNE2 can inhibit the development of non-small cell lung cancer cells." (PMID 38994350, 2024). "ZYG11A is an oncogene in non-small cell lung cancer (NSCLC) and it influences CCNE1 expression." (PMID 37032811, 2023). "Similarly, miR-144 in BMSC-Exos could down-regulate the expression levels of CCNE1 and CCNE2, thereby regulating the cell proliferation and cell cycle progression in non-small cell lung cancer (NSCLC), and further inhibiting NSCLC progression." (PMID 39161894, 2024).
breast tumors (16 papers, 2004 to 2025). "We found that cyclin E1 is stabilized in BRCA1 mutated breast tumors in association with reduced phosphorylation on cyclin E1 Threonine 62, and high cyclin E1 is associated with decreased overall survival for patients with BRCA1 mutation." (PMID 34465787, 2021). "The single breast tumor that we identified with both BRCA1 mutation and CCNE1 amplification (PD13296a) had the highest number of rearrangements related to the RS1 signature (n = 1221) across all the tumors we analyzed." (PMID 30531861, 2018). "In both ovarian tumor data sets analyzed the minimal mapped region of gain incorporated the same five genes (POP4, PLEKHF1, C19orf12, CCNE1 and C19orf2), with similar overlapping regions detected in endometrial and breast tumors." (PMID 21103391, 2010). "We next assessed CCNE1 expression in human breast tumors (TCGA)." (PMID 35173014, 2022). "More recently, a 19q12 amplification was detected, primarily associated with grade III breast tumors in estrogen-negative samples, which encompasses the CCNE1 gene, among others." (PMID 25391423, 2015). "It is known that CCNE1 and CCNE2 genes are directly or indirectly controlled by c-Myc pathways during mouse development and breast tumors driven by c-Myc." (PMID 27527859, 2016). "Moreover, Roquin1 expression was negatively correlated with CCNE1 and MCM2 in human breast tumors." (PMID 33228782, 2020). "In addition, JUNB protein levels correlated with cyclin E1 and TGFB2 protein levels, suggesting that high JUNB protein levels may also promote aggressiveness of breast tumors by positively controlling their expression with consequences on both cell proliferation and invasion." (PMID 36494864, 2022). "As expected, the stem–loop sequences in the 3’UTRs of CCNE1 and MCM2 could be amplified in the GFP antibody pulldown group but not in the group using isotype IgG, indicating the binding of Roquin1 to the 3’UTRs of cell cycle–promoting mRNAs in breast tumor cells." (PMID 33228782, 2020).
colon carcinoma (16 papers, 2014 to 2025). "Wnt signaling is aberrantly activated in approximately 80% of colon cancers, and its downstream genes, including cyclin D1, cyclin E1, and c-Myc, are implicated in the proliferation and metastasis of colon cancer cells." (PMID 40104500, 2025). "Despite the established role of cyclin E1 in colon cancer promotion, long-term survival was associated with high CCNE1 expression." (PMID 33919332, 2021). "miR-136 offers a novel pathway for the inhibition of Wnt signaling by significantly reducing the expression of cyclin D1, cyclin E1, and c-Myc in colon cancer through LRH-1 suppression." (PMID 40104500, 2025). "Promotes degradation of cyclin E1, potentially inhibiting cell cycle progression and tumor growth in colon cancer." (PMID 41373479, 2025). "In this study, we identified six cyclin genes (CCNA2, CCNB1, CCND1, CCNE1, CCNF, and CCNJL) that are potential diagnostic biomarkers of colon cancer." (PMID 33996604, 2021). "It has been reported in the literature that the high expression of CCNE1 was closely related to the poor clinical prognosis of patients with various malignancies such as ovarian, bladder and colon cancer." (PMID 33449451, 2021). "Collectively, these results demonstrated that the depletion of MSI2 delayed the G1-to-S phase transition by regulating the amount of Cyclin E1 expression in colon cancer HCT116 cells, thus suppressing its proliferation." (PMID 35153752, 2021). "In addition, the expression of cyclin-related proteins (Cyclin C, Cyclin D1, Cyclin E1) in colon cancer cell HT29 in each group was determined by western blot." (PMID 35615948, 2022). "However, it seems that the significance of CCNA2 and CCNE1 for the prognosis of colon cancer hasn’t been elucidated yet." (PMID 33996604, 2021). "In the present study, we found that P-selectin deficiency inhibited the direct interaction between platelets and colon cancer cells, thus reducing tumor growth by modulating the expression of genes involved in cell cycle progression, such as CyclinD1, Ccne1 and Pcna." (PMID 34439397, 2021). "Cellular experiments confirmed aspirin downregulated metastasis‐related genes (E2F1, CCNE1, VEGFA, MMP3) in colon cancer." (PMID 41425852, 2025). "Given the potential of the four important cyclin genes (CCNA2, CCNB1, CCNE1, and CCNF), we further investigated the genes co-expressed with them in colon cancer via WGCNA." (PMID 33996604, 2021). "Analysis of dataset GSE29623, an mRNA and microRNA profile in colon cancer, supported that miR-622 positively correlated with signature genes in cell cycle pathway, such as CDC6 (r = 0.421), CDK2 (r = 0.336), CCNE1 (r = 0.423), CCNA2 (r = 0.412), CCNA5 (r = 0.350), and MCM10 (r = 0.423)." (PMID 38166756, 2024). "Overall, patients with lower expression of the four genes (CCNA2, CCNB1, CCNE1, and CCNF) had worse survival outcomes, which implies that these members of the cyclin family might be ideal prognostic biomarkers for colon cancer." (PMID 33996604, 2021). "In addition, we confirmed at the cellular level that aspirin has the ability to inhibit the metastasis of colon cancer cells and demonstrated that aspirin can suppress the expression of metastasis‐related genes (E2F1, VEGFA, MMP3, and CCNE1) in colon cancer cells." (PMID 41425852, 2025). "Importantly, aspirin also inhibited the expression of four highly expressed metastatic genes in colon cancer, including E2F1, CCNE1, VEGFA, and MMP3, which may explain its anti‐tumor and anti‐metastasis effect." (PMID 41425852, 2025). "Among the four datasets of colon cancer from The Cancer Genome Atlas and the Gene Expression Omnibus, six cyclin genes (CCNA2, CCNB1, CCND1, CCNE1, CCNF, and CCNJL) were differentially expressed between normal and tumor tissues." (PMID 33996604, 2021).
lung adenocarcinoma (16 papers, 2018 to 2025). A carcinoma that arises from the lung and is characterized by the presence of malignant glandular epithelial cells. "LINC00355 knockdown suppressed cell proliferation, facilitated cell apoptosis in lung adenocarcinoma cells, and hampered tumor growth in lung adenocarcinoma xenografts by reducing microRNA-195 expression and increasing cyclin E1 expression." (PMID 33381451, 2020). "Upregulation of CCNE1 expression in tumour samples was also seen when we analysed lung adenocarcinoma and lung squamous cell carcinoma datasets from the TCGA database." (PMID 29570800, 2018). "NDC80, CENPL, ORC1, CENPN, CCNE1, and CCNB2 were significantly upregulated in the TCGA cohort as well as in the 18 pairs of lung adenocarcinoma patient samples, and high expression was significantly associated with poor prognosis in lung adenocarcinoma." (PMID 37123398, 2023). "Similarly, simultaneous overexpression of miR-497 and miR-34a leads to enhanced suppression of the oncogene Cyclin E1 in lung adenocarcinoma cells and also in a murine tumor xenograft model." (PMID 35758143, 2022). "However, lung adenocarcinoma patients with low CCNE1 expression had a statistically significant longer OS than those with high CCNE1 expression." (PMID 29570800, 2018). "The results showed that the level of DNA methylation was negatively related to the decreased CCNE1 and E2F1 transcription in 370 lung squamous cell carcinoma tissues (p < 0.05) and 456 lung adenocarcinoma tissues (p < 0.05)." (PMID 33613291, 2021). "In lung adenocarcinoma cells, the expression of CCNE1, but not CCND1, was positively correlated with the CDCA2 levels." (PMID 35694386, 2022). "Then the correlation analysis of DNA methylation level and transcript level of CCNE1 and E2F1 in 370 lung squamous cell carcinoma and 456 lung adenocarcinoma tissues from TCGA cohort was performed to identify the possible mechanism underlying CCNE1 and E2F1 DNA methylation in NSCLC by cBioPorta." (PMID 33613291, 2021). "HOXC13 promotes proliferation of lung adenocarcinoma via modulation of CCND1 and CCNE1." (PMID 31992202, 2020).
melanoma (16 papers, 2011 to 2025). A malignant, usually aggressive tumor composed of atypical, neoplastic melanocytes. "In B16F10 melanoma cells, palbociclib decreased protein levels of cyclin A2 but increased cyclin D1 and cyclin E1 protein levels." (PMID 40904502, 2025). "Accordingly, Cyclin E1 overexpression in canine melanoma cells may similarly contribute to abemaciclib resistance." (PMID 40642276, 2025). "In 1014 melanoma cells, even with high-dose CDK2 inhibition, addition of the CDK4/6 inhibitor was required to suppress cyclin E1 levels." (PMID 40904502, 2025). "For example, the RB1 pathway is a primary driver of skin cancers, with mutations in RB1, CDKN2A/p16, CDKN1A/p21, CDKN1B/p27, CDKN2B/p15, CCNE1/cyclin E, and CCND1/cyclin D, collectively, in 26.4% of melanomas." (PMID 34983823, 2022). "The RT–PCR results showed that compared to the control, the mRNA levels of cell cycle proteins, such as cyclin E1 and CDK2, were enhanced in PRPS1-overexpressing melanoma cells, but the mRNA level of P16 was inhibited." (PMID 36203561, 2022). "HuR-NP treatment significantly diminished protein expression of HuR, Cyclin D1, Cyclin E1, BCL-2, HIF1-α, VEGEF-A, and an increased expression of p27 at both 24 h and 48 h in melanoma cell lines (p < 0.05)." (PMID 33418925, 2021). "The results of real-time PCR and Western blot for mRNA and protein expression levels of cell cycle-related factors showed that in melanoma cells with NOD2 overexpression, Cyclin E1/D1 and CDK2/4 expression levels were downregulated while promoting P27 expression." (PMID 39353904, 2024). "The western blotting results showed that the protein levels of cyclins such as cyclin E1 and CDK2 were increased in PRPS1-overexpressing melanoma cells, while the level of P16 was decreased compared with the control group, while the opposite was true in PRPS1 knockdown A875 and SK-MEL-110 cells." (PMID 36203561, 2022). "Since HuR knockdown reduced cyclin D1 and cyclin E1 and concomitantly increased the expression of p27, we evaluated the cell cycle profile of melanoma (MeWo and A375) and melanocytes with and without the HuR-NP exposure." (PMID 33418925, 2021). "This set of genes included forkhead box C1 (FOXC1), keratin 14 (KRT14), cyclin E1 (CCNE1), melanoma inhibitory activity (MIA) and secreted frizzled-related protein 1 (SFRP1), while expression of CDCA1 and MELK, (neither of which were detectable in MCF7), did not change following SOX11 depletion." (PMID 26894864, 2016).
ovarian tumors (16 papers, 2010 to 2025). "Co-amplified genes were also prominent in the high-risk ovarian tumors including case OC-04 with high level CCNE1 amplification and co-amplification of CCND1, CCND3, MYC and ETV6 genes." (PMID 23289505, 2013). "We identified copy number change of three loci at 20q11, 1p36 and 6q27 to be significantly associated with CCNE1 amplification in ovarian tumors." (PMID 21103391, 2010). "Recurrent amplifications of the CCNE1 gene region on chromosome 19q, which encodes cyclin E, were reported in ovarian tumors by Etemadmoghadam and colleagues who used siRNA-mediated knockdown studies to show CCNE1 to be the amplicon driver of the oncogenic phenotype." (PMID 23289505, 2013). "As ovary tumors with elevated CCNE1 level often exhibit higher Cdk2 expression and most of CCNE1-associated tumor promoting effects require the participation of Cdk2, we reasoned that targeting Cdk2 may be an attractive alternative given the current availability of small molecule Cdk2 inhibitors." (PMID 26204491, 2015). "Single-cell RNA sequencing (scRNA-seq) and spatial transcriptomic data from cervical, endometrial, and ovarian tumors were used to investigate CCNE1 expression patterns, cell type specificity, and microenvironmental interactions." (PMID 41331376, 2025). "Utilising cBioPortal, we observed that 22% of ovarian tumours (TCGA, Firehose Legacy, n = 311) had CCNE1 gene amplification (n = 67/311)." (PMID 38612869, 2024). "Approximately 40% of high-grade serous HR proficient ovarian tumours, demonstrate increased Cyclin E expression by CCNE1 gene amplification, increased copy numbers or enhanced protein expression." (PMID 35800366, 2022). "To understand this differentiation, we examined CCNE1 staining in human ovarian tumor specimens by performing immunohistochemistry on a tissue array that contained normal, benign and ovarian tumor tissues." (PMID 26204491, 2015). "Consistent with published immunohistochemistry studies, we showed that over 40% of primary ovary tumor specimens were positive for CCNE1 staining." (PMID 26204491, 2015). "In conclusion, our study has laid a foundation on using currently available Cdk2 inhibitor for ovary tumors that exhibit elevated CCNE1 expression." (PMID 26204491, 2015). "Elevation of CCNE1 level has been reported in various histological types of human ovarian tumors including HGSOC." (PMID 26204491, 2015). "CCNE1 copy number was measured in 43 primary ovarian tumors from patients with advanced-stage, serous invasive disease." (PMID 21103391, 2010). "In both clear cell ovarian carcinoma (CCOC) and high-grade serous ovarian carcinoma (HGSOC), CCNE1 expression is largely confined to epithelial cells, supporting previous bulk genomic findings that identified CCNE1 as a lineage-specific driver of ovarian tumors proliferation." (PMID 41331376, 2025). "Therapies that target this aspect may provide an opportunity to improve outcomes by tailoring the treatment regimen for patients with CCNE1-amplified ovarian tumors." (PMID 37250533, 2023). "CCNE1 is an example of an amplified oncogene in ovarian tumors." (PMID 33488950, 2020). "This study suggests that ovary tumors with elevated CCNE1 expression may be staged for Cdk2-targeted therapy." (PMID 26204491, 2015). "Moreover, SNS-032 greatly prolonged the survival of mice bearing ovary tumors with inherent CCNE1 overexpression." (PMID 26204491, 2015). "CCNE1 gene amplification is present in 15-20% ovary tumor specimens." (PMID 26204491, 2015). "Immunohistochemistry studies further indicate that CCNE1 overexpression may contribute the malignancies of ovary tumors." (PMID 26204491, 2015). "Thus ovarian tumor cells with amplification at 19q12 are specifically sensitive to depletion of Cyclin E1, compared with unamplified lines." (PMID 21103391, 2010).
ovarian tumors (continued). "Interfering with CCNE1 function may be an effective strategy to suppress CCNE1-overexpressing ovary tumors, the nature of CCNE1 as a regulatory subunit of CDK complex rather than as an enzyme or receptor indicates that CCNE1 itself is not likely to be an ideal drug target." (PMID 26204491, 2015). "Knockdown of FLOT1 by FLOT1‐siRNA inhibits the proliferation of OC cells and arrests the cell cycle at the S phase, whereas suppression of FLOT1 increases cyclin E1 protein, indicating that FLOT1 plays an important role in ovarian tumor growth." (PMID 40066501, 2025). "A higher expression of CCNE1 mRNA was observed in the ovarian tumours compared to the normal tissue." (PMID 38612869, 2024). "We also showed that CCNE1 was stained positive in over 40% of primary ovary tumor specimens regardless of their histological types while CCNE1 staining was either negative or low in normal ovary and benign ovary tumor tissues." (PMID 26204491, 2015). "Although CCNE1 staining was negative or low in all normal ovary tissues or benign ovary tumor specimens, we did not detect a correlation between CCNE1 staining and pathological grades in ovary tumor specimens." (PMID 26204491, 2015). "Immunohistochemistry study with primary ovary tumor specimens showed that over 40% of ovary tumor specimens were positive for CCNE1 staining; in contrast, CCNE1 staining was either negative or very low in normal ovary and benign ovary tumor specimens." (PMID 26204491, 2015). "CCNE1 amplifications may occur later in breast and ovarian tumors, not leaving enough time for rearrangements to accumulate." (PMID 30531861, 2018). "We did not explore the in vivo effects of CCNE1 knockdown in ovarian tumor lines with 19q12 amplification, as we were unable to generate viable lines with stable lentivirus integration of short hairpin RNA (shRNA) directed to CCNE1 (data not shown)." (PMID 21103391, 2010). "Except for ATAD2, expression of other genes (ASF1B, CCNE1, CDC20, CDCA8, RECQL4, RNASEH2A, and SMC4) was upregulated in ovarian tumors compared to non-cancerous tissue." (PMID 39199556, 2024).